TLE5 (TLE family member 5, transcriptional modulator)
Description:
Transcriptional corepressor. Acts as a dominant repressor towards other family members. Inhibits NF-kappa-B-regulated gene expression. May be required for the initiation and maintenance of the differentiated state. Essential for the transcriptional repressor activity of SIX3 during retina and lens development.
Synonyms: AES; GRG; GRG5; AES-1; AES-2; ESP1; Grg-5
Tractability: PROTAC: UniProt records ubiquitination sites on it; ubiquitination databases record sites on it.
Gene: Protein-coding gene on chromosome 19 (3,052,909 to 3,063,107, reverse strand). Ensembl gene ENSG00000104964.
Subcellular location: Nucleus
Subcellular location (Human Protein Atlas): Nucleoplasm
Pathways (Reactome):
Signal Transduction: Repression of WNT target genes
Gene Ontology:
Molecular function: protein binding; transcription corepressor activity
Biological process: negative regulation of canonical Wnt signaling pathway; negative regulation of DNA-templated transcription; negative regulation of gene expression; negative regulation of response to cytokine stimulus; negative regulation of transcription by RNA polymerase II; positive regulation of anoikis; response to interleukin-1; regulation of DNA-templated transcription
Cellular component: nucleus
Genetic constraint (gnomAD): Loss-of-function variants: 6 observed, 18.77 expected, observed/expected ratio (o/e) 0.32, 90% interval 0.17 to 0.63. The upper end of that interval is the gene's LOEUF score, 0.63, which puts it in group 2 of 6, group 1 being the genes least tolerant of losing a copy. Missense variants: 149 observed, 244.55 expected, observed/expected ratio (o/e) 0.61, 90% interval 0.53 to 0.7. Synonymous variants: 132 observed, 114.38 expected, observed/expected ratio (o/e) 1.15, 90% interval 1 to 1.33.
Homologues: Orthologues: dog TLE5 (100% identical), pig TLE5 (100% identical), mouse Tle5 (99% identical), chimpanzee TLE5 (95% identical), guinea pig TLE5 (95% identical), rat Tle5 (95% identical), tropical clawed frog tle5 (89% identical), zebrafish tle5 (81% identical), zebrafish chico (80% identical). Paralogues in human: TLE4 (68% identical), TLE1 (66% identical), TLE3 (63% identical), TLE2 (63% identical), TLE6 (10% identical), TLE7 (8% identical).
Diseases named in the same sentence as TLE5 in open-access papers:
TLE5 is named in the same sentence as 30 diseases in open-access papers, as found by Europe PMC text mining. Sharing a sentence is not in itself a finding about the gene and the disease. The quoted sentences say what the papers report.
colon carcinoma (3 papers, 2014 to 2022). "CK1δ and CK1ε are overexpressed in colon cancer and are inversely correlated with low TLE5 expression." (PMID 36438567, 2022). "Intriguingly, TLE1 alone could not suppress Notch signaling in colon cancer cells, but it could potentiate the suppressive activity of TLE5 by forming distinct nuclear foci containing TLE1, TLE5, and HDAC3." (PMID 36438567, 2022).
colorectal cancer (2 papers, 2021 to 2022). A primary or metastatic malignant neoplasm that affects the colon or rectum. "In addition, TLE5 inhibits the metastasis of colorectal cancer and prostate cancer by inhibiting the Notch and androgen receptor (AR) signaling pathways." (PMID 36438567, 2022). "In addition, TLE5 may recruit HDAC3 to the promoter of Notch target genes in colorectal cancer cells to suppress transcription, and interestingly, these effects depend on unique TLE complexes formed by TLE1 and TLE5 in the nucleus." (PMID 36438567, 2022).
prostate carcinoma (2 papers, 2010 to 2022). A carcinoma that arises from epithelial cells of the prostate gland. "Similarly, TLE5 suppressed prostate cancer metastasis by inhibiting AR and Notch signaling, and loss of TLE5 promoted tumor invasion and metastasis by increasing Snail and MMP9 expression." (PMID 36438567, 2022). "TLE5 directly interacts with AR and prevents AR from binding DNA, thus suppressing ligand-dependent AR target gene expression and inhibiting prostate cancer progression and metastasis." (PMID 36438567, 2022). "The ubiquitin‒proteasome degradation system seems to play a critical role in regulating TLE3 levels; however, the mechanisms by which TLE5 is suppressed in metastatic colon and prostate cancers are not fully understood." (PMID 36438567, 2022).
co-infection (1 paper, 2025). "In the present work, we further investigated how this interspecies competition may regulate host cell responses in the case of co-infection, highlighting further the role of the T6SS and its 2 effector molecules, Tle5 and Glh." (PMID 40574274, 2025).
septicemia (1 paper, 2022). "In P. aeruginosa, the production of Tle5 and ExoU is correlated with a high risk of exacerbations in non-CF patients and with acute pulmonary infection, septicemia and, in a lesser extent, UTIs." (PMID 35782124, 2022).
tumor (8 papers, 2010 to 2023). "Consistently, treatment with a CK1 inhibitor suppressed tumor growth by stabilizing TLE5." (PMID 36438567, 2022). "TLE5 also plays a tumor suppressive role in clonal cancer metastasis." (PMID 36438567, 2022). "Consistently, knocking down TLE5 enhanced tumor invasiveness by activating Notch signaling." (PMID 36438567, 2022).
cancer (7 papers, 2010 to 2024). A tumor composed of atypical neoplastic, often pleomorphic cells that invade other tissues. "TLE5 overexpression inhibited Notch signaling activation through recruitment of TLE1 and HDAC3, converting active Notch transcriptional complexes into repressive complexes, which reduced the expression of Notch target genes such as HES1 in clone cancer cells." (PMID 36438567, 2022). "However, in cancer cells, overexpression of TLE1 can suppress anoikis by competing with TLE5 for Bit binding and sequestering TLE5 in the nucleus." (PMID 36438567, 2022).
TLE5 also shares sentences with these, for which no sentence is quoted: breast carcinoma (3 papers); lung carcinoma (3); colorectal tumor (2); leukemia (2); amnesia (1); bone disorder (1); cervical cancer (1); colon adenocarcinoma (1); cystic fibrosis (1); esophageal cancer (1); gastric cancer (1); hepatocellular carcinoma (1); infection (1); liver cancer (1); liver disease (1); lung adenocarcinoma (1); neuroblastoma (1); neurological disorders (1); osteoporosis (1); osteosarcoma (1); retinoblastoma (1); sarcoma (1); teratoma (1).